SNORD116-4 (small nucleolar RNA, C/D box 116-4)
Synonyms: HBII-85-4
Gene: Small nucleolar RNA gene on chromosome 15 (25,059,538 to 25,059,633, forward strand). Ensembl gene ENSG00000275529.
Gene Ontology:
Biological process: RNA processing
Cellular component: nucleolus
Homologues: Orthologues: macaque SNORD116 (97% identical), rabbit SNORD116 (88% identical), rabbit SNORD116 (86% identical), rabbit SNORD116 (85% identical), rabbit SNORD116 (84% identical), rabbit SNORD116 (81% identical), rabbit SNORD116 (78% identical), rabbit SNORD116 (76% identical), rabbit SNORD116 (75% identical). Paralogues in human: SNORD116-2 (96% identical), SNORD116-3 (96% identical), SNORD116-6 (96% identical), SNORD116-8 (96% identical), SNORD116-9 (96% identical), SNORD116-5 (95% identical), SNORD116-7 (95% identical), SNORD116-1 (93% identical), SNORD116-14 (85% identical), SNORD116-17 (84% identical), SNORD116-19 (84% identical), SNORD116-21 (84% identical), and 20 more.